ISM2 (isthmin 2)
Synonyms: TAIL1; THSD3; FLJ32147
Tractability: Antibody: UniProt places it where antibodies can reach, with high confidence; UniProt predicts a signal peptide or a membrane-spanning region; its Gene Ontology location is reachable by antibodies, with medium confidence.
Gene: Protein-coding gene on chromosome 14 (77,474,394 to 77,499,408, reverse strand). Ensembl gene ENSG00000100593.
Subcellular location: Secreted
Subcellular location (Human Protein Atlas): Nucleoplasm; Centrosome; Cytosol; Predicted to be secreted
Gene Ontology:
Molecular function: protein binding
Cellular component: extracellular region
Genetic constraint (gnomAD): Loss-of-function variants: 49 observed, 55.07 expected, observed/expected ratio (o/e) 0.89, 90% interval 0.71 to 1.13. The upper end of that interval is the gene's LOEUF score, 1.13, which puts it in group 4 of 6, group 1 being the genes least tolerant of losing a copy. Missense variants: 721 observed, 722.35 expected, observed/expected ratio (o/e) 1, 90% interval 0.94 to 1.06. Synonymous variants: 303 observed, 293.77 expected, observed/expected ratio (o/e) 1.03, 90% interval 0.94 to 1.13.
Homologues: Orthologues: chimpanzee ISM2 (97% identical), rat Ism2 (57% identical), macaque ISM2 (57% identical), mouse Ism2 (57% identical), dog ISM2 (50% identical), Caenorhabditis elegans F11C7.6 (6% identical), Caenorhabditis elegans F11C7.7 (5% identical).
Diseases named in the same sentence as ISM2 in open-access papers:
ISM2 is named in the same sentence as 14 diseases in open-access papers, as found by Europe PMC text mining. Sharing a sentence is not in itself a finding about the gene and the disease. The quoted sentences say what the papers report.
choriocarcinoma (4 papers, 2020 to 2023). An aggressive malignant tumor arising from trophoblastic cells. "Interestingly, ISM2 is mainly expressed in the placenta and has been associated with preeclampsia and choriocarcinoma." (PMID 37047617, 2023). "ISM2 is expressed at high levels in the placenta and is overexpressed in cases of choriocarcinoma, consistent with the invasive nature of PAS21." (PMID 36604494, 2023). "In summary, ISM1 upregulation and overexpression are reported in multiple cancers, including gastric cancer, hepatocellular carcinoma (HCC), colon adenocarcinoma, and colorectal cancer, while ISM2 overexpression was reported in choriocarcinoma." (PMID 36611811, 2022). "Our findings open to new studies that allow us to elucidate the participation of ISM2 in the development of preeclampsia, and moreover to characterize its potential angiogenic function in choriocarcinoma and other cancers." (PMID 33088937, 2020). "We also performed immunohistochemistry of ISM2 in samples from choriocarcinoma and compare with lung, prostate, colon, gastric and breast cancers." (PMID 33088937, 2020). "Furthermore, strong expression of ISM2 is observed in choriocarcinoma, while moderate expression in lung and prostate adenocarcinoma is observed and mild expression is indicated in colon adenocarcinoma and cohesive gastric carcinoma." (PMID 36611811, 2022). "We also found that ISM2 protein was overexpressed in choriocarcinoma." (PMID 33088937, 2020). "In this study we were interested in assessing whether ISM2 protein is dysregulated in preeclampsia and choriocarcinoma, considering that both diseases involved placenta dysfunction." (PMID 33088937, 2020). "On the contrary, we found that ISM2 shows a strong expression in choriocarcinoma." (PMID 33088937, 2020). "Its serum level decreased in our patients with preeclampsia could be reflecting that it is involved in the pathogenesis of the disease; on the other hand its high expression in choriocarcinoma, indicates that ISM2 may play an active role in the angiogenesis of this and other cancers." (PMID 33088937, 2020). "In addition, ISM2 may also play a role in the angiogenesis of choriocarcinoma." (PMID 33088937, 2020).
preeclampsia (3 papers, 2020 to 2023). Preeclampsia is a hypertensive disorder of pregnancy that is characterized by new-onset hypertension with proteinuria presenting after 20 weeks of gestation, and depending on mild or severe forms may initially present with severe headache, visual disturbances, and hyperreflexia. "Circulating ISM2 was only statistically significant decreased in women with preeclampsia compared with the control group." (PMID 33088937, 2020). "The ISM2 protein was found to be decreased in patients with preeclampsia compared to the control group (P = 0.036)." (PMID 33088937, 2020). "On the other hand, in upcoming researches to compare the levels of ISM2 with angiogenic factors already described in preeclampsia as PlGF, and VEGF, is a mandatory next stage." (PMID 33088937, 2020). "The level of ISM2 in the gestational hypertension group was 3.5–655.2 pg/mL with a median of 82.6 pg/mL." (PMID 33088937, 2020). "The serum levels of ISM2 protein were measured in 30 patients with normotensive pregnancy, 21 patients with gestational hypertension and 30 patients with preeclampsia." (PMID 33088937, 2020). "We showed that patients with preeclampsia have decreased serum levels of ISM2 protein in relation to normal pregnancy and gestational hypertension." (PMID 33088937, 2020). "This is the first study conducted to evaluate the ISM2 protein in preeclampsia and choriocarcinoma, a protein with almost specific expression in placenta." (PMID 33088937, 2020). "The level of ISM2 in the control group was 3.5–1000 pg/mL with a median of 110 pg/mL and in the preeclampsia group was 3.5–467.2 pg/mL with a median of 51.7 pg/mL (P = 0.036)." (PMID 33088937, 2020). "From a clinical perspective, our findings could help to a better diagnosis and prediction of preeclampsia if we are able in next studies to reveal the differences of expression of ISM2 before the onset of preeclampsia and at the disease stage." (PMID 33088937, 2020). "The two contrasting results of ISM2 protein (decreased in preeclampsia and high expression in choriocarcinoma) could have exciting implications." (PMID 33088937, 2020). "We observed a cytoplasmic positivity for ISM2 with difference in the immunohistochemical staining whether the tissue was derived from preeclampsia, gestational hypertension or control group." (PMID 33088937, 2020). "We conclude that ISM2 is a protein with angiogenic function, which shows under normal conditions its highest expression in placenta and decreases in pregnant women with preeclampsia." (PMID 33088937, 2020).
gastric cancer (1 paper, 2025). A primary or metastatic malignant neoplasm involving the stomach. "CLEC4M and F5 were significantly associated with the gastric cancer grade, and mutations in ISM2 and F5 were more likely to be found in well-differentiated tumors." (PMID 39870503, 2025).
mucinous tumors (1 paper, 2022). "For example, the IHC data showed intense extracellular positivity of ISM2 in classical adenocarcinomas compared with mucinous tumors, reflecting the differences in gene expression profiles." (PMID 35953834, 2022).
cancer (4 papers, 2020 to 2025). A tumor composed of atypical neoplastic, often pleomorphic cells that invade other tissues. "Finally, despite the negative correlation between ISM1/Isthmin 1 and VEGF in cancer context, literature data correlating ISM2/Isthmin 2 with VEGF are still lacking, although a possible interaction could be hypothesised based on its pro- or anti-angiogenic properties." (PMID 37047617, 2023).
tumor (1 paper, 2021). "MSGN1, ISM2, HAS1, RETN, MMP19, C1QTNF1, and F13A1 were all involved in the regulation of tumors, but their involvement in the regulation of tumor immunity is not clear." (PMID 34177903, 2021).
ISM2 also shares sentences with these, for which no sentence is quoted: colon adenocarcinoma (2 papers); adenocarcinoma (1); breast carcinoma (1); hepatocellular carcinoma (1); invasive ductal carcinoma (1); lung adenocarcinoma (1); neuroblastoma (1); prostate adenocarcinoma (1).